FGF20 (fibroblast growth factor 20)
Description:
Neurotrophic factor that regulates central nervous development and function.
Synonyms: FGF-20; RHDA2
Tractability: Antibody: UniProt places it where antibodies can reach, with high confidence; its Gene Ontology location is reachable by antibodies, with high confidence.
Gene: Protein-coding gene on chromosome 8 (16,992,181 to 17,002,345, reverse strand). Ensembl gene ENSG00000078579.
Subcellular location: Secreted
Pathways (Reactome):
Signal Transduction: Downstream signaling of activated FGFR1; FGFR1c ligand binding and activation; FGFR2c ligand binding and activation; FGFR3b ligand binding and activation; FGFR3c ligand binding and activation; FGFR4 ligand binding and activation; FRS-mediated FGFR1 signaling; FRS-mediated FGFR2 signaling; FRS-mediated FGFR3 signaling; FRS-mediated FGFR4 signaling; Negative regulation of FGFR1 signaling; Negative regulation of FGFR2 signaling; Negative regulation of FGFR3 signaling; Negative regulation of FGFR4 signaling; PI-3K cascade:FGFR1; PI-3K cascade:FGFR2; PI-3K cascade:FGFR3; PI-3K cascade:FGFR4; PI3K Cascade; PI5P, PP2A and IER3 Regulate PI3K/AKT Signaling; PIP3 activates AKT signaling; Phospholipase C-mediated cascade: FGFR1; Phospholipase C-mediated cascade; FGFR2; Phospholipase C-mediated cascade; FGFR3; Phospholipase C-mediated cascade; FGFR4; RAF/MAP kinase cascade; SHC-mediated cascade:FGFR1; SHC-mediated cascade:FGFR2; SHC-mediated cascade:FGFR3; SHC-mediated cascade:FGFR4
Disease: Activated point mutants of FGFR2; Constitutive Signaling by Aberrant PI3K in Cancer; Signaling by FGFR1 in disease; Signaling by FGFR2 in disease; Signaling by FGFR3 in disease; Signaling by activated point mutants of FGFR1; Signaling by activated point mutants of FGFR3
Gene Ontology:
Molecular function: receptor-receptor interaction; fibroblast growth factor receptor binding; growth factor activity; heparan sulfate proteoglycan binding; signaling receptor binding
Biological process: negative regulation of neuron apoptotic process; cell-cell signaling; fibroblast growth factor receptor signaling pathway; neurogenesis; positive regulation of cell population proliferation; positive regulation of dopaminergic neuron differentiation; positive regulation of MAPK cascade; regulation of cell migration; regulation of dopamine secretion; signal transduction; regulation of neuron differentiation
Cellular component: cytoplasm; extracellular region
Genetic constraint (gnomAD): Loss-of-function variants: 5 observed, 9.18 expected, observed/expected ratio (o/e) 0.54, 90% interval 0.28 to 1.14. That is too few expected variants to judge how well the gene tolerates losing a copy. Missense variants: 347 observed, 206.35 expected, observed/expected ratio (o/e) 1.68, 90% interval 1.54 to 1.84. Synonymous variants: 140 observed, 87.87 expected, observed/expected ratio (o/e) 1.59, 90% interval 1.39 to 1.83.
Homologues: Orthologues: chimpanzee FGF20 (100% identical), macaque FGF20 (99% identical), pig FGF20 (98% identical), dog FGF20 (97% identical), mouse Fgf20 (95% identical), rat Fgf20 (95% identical), guinea pig FGF20 (80% identical), tropical clawed frog fgf20 (79% identical), zebrafish fgf20b (76% identical), zebrafish fgf20a (71% identical). Paralogues in human: FGF9 (70% identical), FGF16 (64% identical), FGF5 (35% identical), FGF3 (33% identical), FGF6 (33% identical), FGF10 (32% identical), FGF4 (32% identical), FGF22 (31% identical), FGF7 (31% identical), FGF11 (30% identical), FGF14 (30% identical), FGF13 (29% identical), and 9 more.
Diseases named in the same sentence as FGF20 in open-access papers:
FGF20 is named in the same sentence as 34 diseases in open-access papers, as found by Europe PMC text mining. Sharing a sentence is not in itself a finding about the gene and the disease. The quoted sentences say what the papers report.
Parkinson disease (26 papers, 2005 to 2025). A progressive degenerative disorder of the central nervous system characterized by loss of dopamine producing neurons in the substantia nigra and the presence of Lewy bodies in the substantia nigra and locus coeruleus. "Risk variants of other FGF20 genetic variation have been linked to an increased risk of Parkinson disease." (PMID 37085326, 2023). "The highly significant correlation of Parkinson's disease with one SNP located in the intron and two SNPs in the 3′ regulatory region was revealed, which indicated that Fgf20 genetic variability is a risk factor for Parkinson's disease." (PMID 23754977, 2013). "The significant correlation of Parkinson's disease with single-nucleotide polymorphisms in FGF20 indicates that the genetic variability of FGF20 can be a Parkinson's disease risk." (PMID 23754977, 2013). "Another gene associated with increased risk of Parkinson's disease in some populations is fibroblast growth factor 20 (FGF20)." (PMID 24133413, 2013). "The significant correlation of Parkinson's disease with SNPs within FGF20 indicated that FGF20 genetic variability is a risk factor for Parkinson's disease." (PMID 23754977, 2013). "In the rat model of Parkinson's disease, Fgf20 affords significant protection against the loss of dopaminergic neurons." (PMID 23754977, 2013). "In the rat model of Parkinson's disease, Fgf20 afforded significant protection against the loss of dopaminergic neurons." (PMID 23754977, 2013). "In the unilateral, 6-hydroxydopamine lesion rat model of Parkinson's disease, supranigral infusion of Fgf20 afforded significant protection against the loss of dopaminergic neurons in the SNpc and striatum." (PMID 23754977, 2013). "miR-101 targets ataxin 1, responsible for SCA1, at both the mRNA and protein levels; miR-433 targets fibroblast growth factor 20 which induces α-synuclein expression, which was previously shown to cause Parkinson’s disease when overexpressed." (PMID 22844398, 2012). "More recently, it has been reported that an apparent gain of function allele of FGF20 is associated with Parkinson's disease and brain structure in human populations." (PMID 22712610, 2012). "Further, mutations in the FGF-20 gene locus have been associated with an increased risk for Parkinson's disease." (PMID 21876757, 2011). "Recently, a strong genetic association has been found between FGF20 gene and the risk of suffering from Parkinson's disease (PD)." (PMID 15967032, 2005). "Moreover, direct intracerebral infusion of FGF20 protects against nigrostriatal tract loss in the 6-hydroxydopamine lesion rat model of Parkinson’s disease." (PMID 31171821, 2019). "In addition, FGF20 genetic variability was shown to be a risk factor for Parkinson's disease in Japanese and Chinese populations, while, was not a risk factor for Parkinson's disease in Finnish and Greek populations." (PMID 23754977, 2013). "The SNP in the 3′ non-coding region of FGF20 can be a risk factor for Parkinson's disease." (PMID 23754977, 2013). "In addition, FGF20 and α-synuclein were also shown to be associated with sporadic Parkinson's disease." (PMID 23754977, 2013). "FGF20 was shown to be a risk factor for Parkinson's disease by the GWAS." (PMID 23754977, 2013). "What is particularly notable about the regional difference is that fgf20 is preferentially expressed in a subregion of the forebrain, the striatum, which contains the majority of dopamine projections, the loss of which results in Parkinson disease." (PMID 17589599, 2007). "However it is evident that the perturbation of epigenetic mechanism (miRNA binding site alteration in FGF20 gene) might be involved in manganese mediated overexpression of α-syn, implicated in the development of Parkinson's disease." (PMID 27314012, 2016).
Parkinson disease (continued). "In silico interrogation of the Broad Institute’s Connectivity Map database (CMap), revealed 50 candidate drugs predicted to increase FGF20 transcription, 16 of which had profiles favourable for use in Parkinson’s disease." (PMID 31171821, 2019). "Further studies on FGF20 will provide useful clues on the etiology and therapy of Parkinson's disease." (PMID 23754977, 2013). "Fgf20 promotes differentiation of cultured cells into dopaminergic neurons, and attenuated neurological symptoms in animal models of Parkinson's disease." (PMID 23754977, 2013). "Fgf20 promoted the differentiation of these stem cells into dopaminergic neurons, which attenuated neurological symptoms in animal models of Parkinson's disease." (PMID 23754977, 2013). "In Parkinson’s disease, a SNP in the 3′ untranslated region of the fibroblast growth factor 20 gene (FGF20) disrupts a binding site for miR-433, increasing translation of FGF20." (PMID 23503168, 2013). "In addition, FGF20 mutations may result in Parkinson's disease." (PMID 23754977, 2013). "Disruption of miR-433 binding site in fibroblast growth factor 20 (FGF20) 3′ UTR correlates with increased alfa-synuclein expression in Parkinson patients." (PMID 22312330, 2012). "It was finally determined that salbutamol and trifluorofloxacin could be used to increase the FGF-20 level to resist the progression of Parkinson's disease." (PMID 34234672, 2021). "Our data demonstrate the power of targeted repositioning as a method to identify existing drugs that may combat disease progression in Parkinson’s by boosting FGF20 levels." (PMID 31171821, 2019). "Boosting the endogenous FGF20 production might offer potential as a future therapeutic strategy in Parkinson's disease." (PMID 29698669, 2018). "Elevated level of FGF20 has been linked with overexpression of α-syn, a characteristic of Parkinson's disease although the mechanistic insight of the process that leads to α-syn overexpression due to elevated FGF20 has not been investigated." (PMID 27314012, 2016). "FGF20 has been mapped to 8p21.3–8p22, which is within an area of Parkinson's disease linkage." (PMID 23754977, 2013). "As these findings indicate that FGF20 may provide useful clues on the etiology and therapy of Parkinson's disease, a succinct review on the roles of FGF20 in dopaminergic neurons and Parkinson's disease has been provided." (PMID 23754977, 2013). "SNP variants in FGF20 and MAOB show evidence of statistical interactions, which emphasizes the importance of considering them jointly in the genetic analysis of Parkinson's disease, and illustrates the potential patterns of biological interactions contributing to the risk of Parkinson's disease." (PMID 23754977, 2013). "For example, if “Parkinson's disease” is entered, the list of validated miRNAs and targets returned are: has-miR-1:BDNF; has-miR-27b:CYP1B1; has-miR-433:FGF20; miR-124:CYP1B1; has-miR-1:GCH1; has-miR125b:CYP1A1." (PMID 23316214, 2012). "Indeed, the relationship of suppressed fgf20 expression to dopaminergic deficits and thence to Parkinson disease is directly supported by human genetic data and by the specific role of this neurotrophic factor in promoting survival of the very neurons that are lost in Parkinson disease." (PMID 17589599, 2007).
brain injury (2 papers, 2020 to 2023). Acute and chronic (see also brain INJURIES, CHRONIC) injuries to the brain, including the cerebral hemispheres, CEREBELLUM, and brain STEM. "FGF20 was shown to be protective in blood–brain barrier (BBB) disruption by upregulating tight junction proteins, increasing the transelectrical endothelial resistance and reducing neuroinflammation in traumatic brain injury models." (PMID 36650549, 2023).
breast carcinoma (2 papers, 2019 to 2022). "Using the SPIEDw algorithm, a long-list of 50 FDA-approved drugs boosting FGF20 gene transcription in human breast carcinoma cells was obtained." (PMID 31171821, 2019). "This interaction is lost during early-stage breast cancer and is controlled by paracrine signalling including FGF10/FGFR2b signalling and FGF20 signalling." (PMID 35193394, 2022). "FGF16 and FGF20 do not have a known role in breast cancer progression." (PMID 35193394, 2022).
glioma (2 papers, 2024 to 2025). A benign or malignant brain and spinal cord tumor that arises from glial cells (astrocytes, oligodendrocytes, ependymal cells). "Conversely, reducing FGF20 expression in glioma cells significantly impairs the effect of GCs on macrophage polarization." (PMID 38962005, 2024). "It has been observed that glucocorticoid (GC) treatment increases FGF20 expression in glioma cells." (PMID 38962005, 2024). "Additionally, this study reveals a molecular connection between glioma cells and macrophages, indicating that FGF20 modulates GC-induced macrophage dysfunction during glioma development." (PMID 38962005, 2024). "FGF20, a paracrine cytokine secreted by glioma cells, has been found to interact with macrophages." (PMID 38962005, 2024).
melanoma (2 papers, 2014 to 2023). A malignant, usually aggressive tumor composed of atypical, neoplastic melanocytes. "Interestingly, the PI3K-Akt signaling pathway shared all genes enriched in melanoma pathway (e.g., CDK6, FGF20, and MITF) and included three additional genes (i.e., RPTOR, COMP, and CDC37), suggesting a higher level of significance and potential relevance." (PMID 37829282, 2023).
mucositis (2 papers, 2009 to 2021). Mucositis is inflammation and damage of the mucous membranes lining the mouth and other parts of the gastrointestinal (GI) tract. "In addition, recombinant human FGF7 (and FGF20) has been used to treat mucositis in response to radiation therapy or as a medical countermeasure against radiation exposure." (PMID 33986387, 2021).
renal agenesis (2 papers, 2020 to 2025). Renal agenesis (RA) is a form of renal tract malformation characterized by the complete absence of development of one or both kidneys (unilateral RA or bilateral RA respectively), accompanied by absent ureter(s). "Inactivating mutations of FGF20 was found to cause bilateral renal aplasia." (PMID 32879300, 2020).
Alzheimer disease (1 paper, 2020). A progressive, neurodegenerative disease characterized by loss of function and death of nerve cells in several areas of the brain leading to loss of cognitive function such as memory and language. "Reports about the therapeutic effects of FGF20 on CNS conditions, except for PD and Alzheimer's disease (AD), are limited." (PMID 33568994, 2020).
cardiac hypertrophy (1 paper, 2022). "In contrast, overexpression of FGF20 protected against pressure overload-induced cardiac hypertrophy." (PMID 35351862, 2022). "Although the expression level of FGF20 in NRCFs did not significantly change the response to ISO stimulation, it is worth exploring the function of endogenous FGF20 in NRCFs in cardiac hypertrophy." (PMID 35351862, 2022). "To validate that the regulatory effects of FGF20 on pathological cardiac hypertrophy were SIRT1-dependent, we generated SIRT1 flox/flox (SIRT1fl/fl) mice and inducible cardiac-specific SIRT1 knockout (SIRT1-iKO) mice." (PMID 35351862, 2022). "In conclusion, our study provides the first evidence that FGF20 not only act as sensor for pressure-induced cardiac hypertrophy, but also maintains redox homeostasis by activating SIRT1-mediated antioxidant defenses." (PMID 35351862, 2022). "Taken together, these data demonstrate that FGF20-mediated prevention of cardiac hypertrophy is related to SIRT1 activation." (PMID 35351862, 2022). "We showed that FGF20 overexpression protected against cardiac hypertrophy both in vitro and in vivo." (PMID 35351862, 2022). "To explore the role of FGF20 in pathological cardiac hypertrophy, we first examined the level of FGF20 in the heart from mice subjected to transverse aortic constriction (TAC) surgery for 6 weeks or sham-operated mice." (PMID 35351862, 2022). "The precise function of FGF20 in pathological cardiac hypertrophy is unclear." (PMID 35351862, 2022). "Based on these findings, we hypothesized that FGF20 prevented cardiac hypertrophy by activating SIRT1-mediated antioxidant defenses." (PMID 35351862, 2022). "Overall, these results imply that FGF20 may play a potential role in cardiomyocytes during the development of cardiac hypertrophy." (PMID 35351862, 2022). "Hence, we aimed to systematically explore the potential function and mechanisms of FGF20 in the pathogenesis of cardiac hypertrophy." (PMID 35351862, 2022). "To determine whether FGF20 improves cardiac hypertrophy in vivo, we used cardiac-specific FGF20 overexpression in mouse heart." (PMID 35351862, 2022). "In summary, our findings reveal a previously unknown protective effect of FGF20 on pathological cardiac hypertrophy by reducing oxidative stress through activation of the SIRT1 signaling pathway." (PMID 35351862, 2022). "FGF20 overexpression experiments were performed to determine whether FGF20 can prevent cardiac hypertrophy, and results showed that overexpression of FGF20 alleviated pathological cardiac hypertrophy." (PMID 35351862, 2022). "Our results suggest that FGF20 could be a promising therapeutic target for the prevention and treatment of pathological cardiac hypertrophy in the clinic." (PMID 35351862, 2022). "Therefore, we examined whether FGF20 protects against cardiac hypertrophy by activating SIRT1 via detecting the protein and transcriptional levels of SIRT1 in vitro and in vivo." (PMID 35351862, 2022). "Furthermore, deletion of SIRT1 restricted the anti-oxidative and anti-apoptotic activities of FGF20 on pathological cardiac hypertrophy; this finding is consistent with our hypothesis." (PMID 35351862, 2022). "Subsequent results revealed that FGF20 overexpression inhibited the upregulation of hypertrophic genes and activation of MAPK signaling pathways, prevented apoptosis and fibrosis, and improved cardiac hypertrophy and dysfunction." (PMID 35351862, 2022). "In addition, mRNA levels of classical markers of cardiac hypertrophy (ANP, BNP, and MYH7) were elevated in TAC-operated mice and were reduced by FGF20 overexpression." (PMID 35351862, 2022). "However, the role of FGF20 in cardiac hypertrophy has not been reported." (PMID 35351862, 2022).
cardiomyopathy (1 paper, 2022). A disease of the heart muscle or myocardium proper. "Of relevance to the current study, FGF9 and FGF16, which belong to the same FGF9 subfamily as FGF20, play pivotal roles in protecting against cardiomyopathy." (PMID 35351862, 2022).
chondrosarcoma (1 paper, 2018). A malignant cartilaginous matrix-producing mesenchymal neoplasm arising from the bone and soft tissue. "Similarly, Fgf signaling induces Cdkn1a-mediated cell cycle arrest in chondrocytes and further, ectopic Fgf20 induces growth arrest of rat chondrosarcoma cells in vitro." (PMID 30063206, 2018).
cognitive decline (1 paper, 2024). "In this study, we found that IP6K2 rs12497850 was associated with cognitive impairment at the time of motor symptoms onset, and FGF20 rs591323 was associated with more rapid cognitive decline after motor symptoms onset." (PMID 38988604, 2024). "IP6K2 was associated with cognitive impairment prior to the onset of motor symptoms and FGF20 was associated with rapid cognitive decline after the onset of motor symptoms in PD." (PMID 38988604, 2024).
Cognitive impairment (1 paper, 2024). Abnormal cognition is characterized by deficits in thinking, reasoning, or remembering. "Multigenetic factors significantly associated with cognitive impairment at early stage of the disease (AUC = 0.950) with IP6K2 rs12497850 more evident, and a significantly faster decline (AUC = 0.831) within 5 years after motor onset, particularly in those carrying FGF20 rs591323." (PMID 38988604, 2024).
colitis (1 paper, 2025). Inflammation of the colon. "This study developed a novel therapeutic strategy by combining decellularized porcine small intestinal submucosa (D-SIS) with fibroblast growth factor 20 (FGF-20) to promote mucosal repair and restore barrier integrity in a TNBS-induced colitis rat model." (PMID 40321695, 2025).
colorectal cancer (1 paper, 2012). A primary or metastatic malignant neoplasm that affects the colon or rectum. "Interestingly, previous studies have shown that TCF/LEF, activated downstream of WNT-β-catenin signaling in colorectal cancer cells, binds to the promoter regions of FGF18 and FGF20." (PMID 22383889, 2012).